TNF (tumor necrosis factor)
Diseases named in the same sentence as TNF in open-access papers (continued):
Sharing a sentence is not in itself a finding about the gene and the disease.
infection (continued). "Type 1 immune responses and the IFN-γ and TNF-α produced by these responses are important to prevent growth of intracellular microbial agents and control dissemination of infections with intracellular agents like Leishmania." (PMID 24485388, 2014). "Compared to the MS_Vec, mRNA levels of TNF-α and IL-1β were significant upregulated in macrophages after 12 hours of infection with MS_Rv3402c." (PMID 24722253, 2014). "This study also shows that the high level expression of three Th-1 cytokines namely IFN-γ, TNF-α and IL-2 by antigen-stimulated spleen cells at the time of infection correlates with the level of protection against L. major infection in mice." (PMID 25500571, 2014). "TNF-α is one of the major inflammatory cytokines that mediates a wide range of biological responses, including inflammation, infection, injury and apoptosis." (PMID 24926361, 2014). "In mouse models of infection, IL-1β, IL-6, and TNF-α are important protective cytokines during S. pneumoniae infection, and we have now demonstrated that expression of these cytokines by healthy controls was largely dependent on lipoproteins." (PMID 25172490, 2014). "Only the IL-10 and TNF-α transcripts showed a significant difference (P < 0.05) between both strains at the peak of infection (resp)." (PMID 24991553, 2014). "After infection, the expression levels of TNF-α and IL-6 in the colon were two-fold higher in PPARγVillinCre+ mice compared to PPARγVillinCre- mice." (PMID 24465207, 2014). "During infection, monocytes produce pro-inflammatory molecules, such as tumor necrosis factor-alpha (TNF-α), interleukin-1 beta (IL-1β), IL-6, and nitric oxide (NO) to destroy pathogens." (PMID 25329066, 2014). "Cytokine analysis at 48 hours after infection showed reduced serum levels of 13 cytokines following anti-TNF-α MAb treatment in both the Ifnar−/− and CD11c Cre+Ifnarf/f mice." (PMID 24743949, 2014). "Eight days after infection, PbT-I cells harvested from the spleen produced IFNγ, TNFα and CD107a, indicating their development of effector function." (PMID 24854165, 2014). "This difference in infection rates between all three anti-TNF agents was statistically significant (P = 0.043)." (PMID 24883246, 2014). "When these basal active infections are taken into account, all viruses, including drug-resistant mutants and WT, showed an approximate 50% increase in virus expression following TNF-α treatment." (PMID 25243372, 2014). "In the BJ501 infection group, TNF-α increased significantly on days 2 but dropped to control level immediately in the following days." (PMID 24725777, 2014). "CR and SJZT alleviated infection-induced interferon-gamma levels in the serum and tissues, and tumor necrosis factor-alpha (TNF-α) levels in intestinal tissues." (PMID 25133542, 2014). "TNF-α regulates a host response to infection; on the other hand, inappropriate expression of TNF-α has detrimental effects for the host." (PMID 25179218, 2014). "On the other hand, live C57BL/6 neutrophils are associated with increased production of neutrophil elastase, thus providing greater activation to macrophages that can better respond to infection with increased production of TNF-α and nitric oxide." (PMID 24599360, 2014). "Three hours post-infection, a significant increase in KC, IL-1β, TNFα, and IL-6 levels was detected in BALs from TLR9-/- compared to WT mice." (PMID 24595157, 2014). "Infection increased lipid peroxidation and the release of TNFα and IFNγ, although capsazepine-treated group exhibited lower levels of lipid peroxidation and TNFα." (PMID 25242870, 2014). "Here, we provided the basic data of expression pattern and histological distribution of NLRP3, IL-1β and TNF-α in lung and brain during infection in BALB/c mice by H9N2 avian influenza virus strains with only a difference at site 627 in PB2." (PMID 25547136, 2014).
infection (continued). "Infection is characterized by up-regulation of inflammatory mediators such as cytokines and chemokines, interleukins, interferon-inducible proteins, and tumor necrosis factor alpha (TNFα)." (PMID 25079789, 2014). "Analysis of the broncho-alveolar lavage fluid (BALF) showed a transient increase in the Th1 cytokines IFN-γ, TNF-α and IL-12 at week 5 post infection." (PMID 25398130, 2014). "For infections with L. naiffi, higher levels of TNF-α and IL-4 were consistently detected in comparison to infections with L. guyanensis and L. amazonensis, though no statistical differences were observed." (PMID 25295285, 2014). "Infection induces the release of cytokines and chemokines including tumor necrosis factor-alpha, interleukin 6, and interleukin 8, which have been proposed as mediators of cancer development." (PMID 24884867, 2014). "TNF-α produced in a local infection site allows macrophages, natural killer (NK) cells and γδ T cells gather at the infection site and bring their activation." (PMID 25317081, 2014). "CD11b+Ly6chighLy6G− inflammatory monocytes are reported to contribute to T. brucei-induced pathogenicity development through their production of TNF, whereby in the acute phase of infection their emigration from the bone marrow is CCL2/CCR2-dependent." (PMID 25255103, 2014). "In A549 lung epithelial cells and human bronchus and lung tissue ex vivo cultures, MERS-CoV SA 1 failed to induce significant expression differences of IFNB1 and TNF genes relative to mock throughout the 72 hour infection course." (PMID 25534508, 2014). "Non-Hb bound heme (free heme) sensitizes non-hematopoietic cells to undergo programmed cell death in response to pro-inflammatory agonists such as tumor necrosis factor (TNF) released in the course of the infection." (PMID 25071574, 2014). "Particularly important is that H1/IC31 induces multifunctional T cells expressing TNF-α and IL-2, markers of central memory T cells, which are required for long-term protection against both reactivation and infection." (PMID 25490675, 2014). "After an initial increase, IL-12α and TNF-α expression decreased dramatically after the 30th day of infection of mice." (PMID 24637903, 2014). "In E. multilocularis lesions, qRT-PCR showed that TNF-α mRNA expression was increased at the early stage of infection, especially at days 2 and 8 p.i.; it remained high at 30 days p.i. but decreased subsequently." (PMID 24637903, 2014). "Infection of RAW264.7 cells with B. anthracis spores induced TNF-α expression in a multiplicity of infection (MOI)-dependent manner, and this enhancement was attenuated by the toll-like receptor (TLR) 9 inhibitor oligodeoxynucleotide (ODN)2088." (PMID 25472474, 2014). "TNF-α, an important cytokine for infection control, is involved in the macrophage activation process and is also an important factor related to disease immunopathology." (PMID 24558401, 2014). "Our results confirmed up-regulation of TGF-β and down-regulation of TNF-α in tissue and serum level in PbA infected peptide treated mice compared to PbA infection." (PMID 24618707, 2014). "TNFα is a key cytokine in the pathogenesis of synovial inflammation in RA, however, it has also been shown to play a vital role in fighting infections in animal models." (PMID 25414636, 2014). "At all time-points, the expression level of TNF-α in VK627 infection group was very significantly higher than rVK627E infection group(P < 0.01)." (PMID 25547136, 2014). "Consistently with our results, other authors also observed an up-regulation of TGFβ and/or IL10 after the infection of bovine MDMs with live Map that down-regulated the production of TNFα." (PMID 25111300, 2014). "In contrast, mice that healed their low dose infection had significantly (p<0.05) higher percentage of proliferating and cytokine- (IFN-γ and TNF) secreting CD8+ T cells than those that healed high dose infection." (PMID 25412267, 2014).
infection (continued). "Levels of tumor necrosis factor-alpha (TNF-α) increased over 6 h after post infection with low dose C. pneumoniae or LPS and remained stable or slightly decreased at later time points." (PMID 25488836, 2014). "At 12 hours post-infection, cells were stimulated with TNFα, and RNA samples were collected at 0, 2, 4, and 6 hours post-TNFα treatment." (PMID 25122471, 2014). "TNFα is a key mediator in the host immune defense against mycobacterium tubercule bacillus (TB) infections leading to activation of macrophages, cell recruitment, granuloma formation and maintenance." (PMID 25414636, 2014). "Although TNF-α is a major mediator of RSV-associated illness in BALB/c mice, it is important in clearance of virus-infected cells during the early stages of infection." (PMID 24700100, 2014). "Later in infection, FP-inoculated mice initiated a strong T cell response, with significantly higher production of IFNγ, TNFα and IL-2 than IN-inoculated mice." (PMID 24922480, 2014). "Infection increased secretion of cytokines/chemokines TNF-α, IL-6, TIMP-1, IL-1RA, G-CSF, TREM, KC, MIP-1α, MIP-1β, MCP-1, and MIP-2 in resident macrophages." (PMID 24416445, 2014). "After 5 days of infection, however, plasma levels TNF-α, monocyte chemo attractive protein (MCP)-1, IL-6, IL-10 and IL-12 were markedly elevated in all WT mice." (PMID 25115174, 2014). "Irrespective of the genotype of mice, IL-6 and IFN-γ serum levels, splenic TNF-α and IFN-γ as well as hepatic TNF-α and IL-6 concentrations increased multifold until day 7 following infection." (PMID 24932221, 2014). "This gains further strength after detection of higher levels of pro-inflammatory cytokines such as IFN-γ and TNF-α and lower level of pleiotropic cytokine IL-6 in these mice during the initial stage of infection." (PMID 25437299, 2014). "Regarding CP-infection, the only significant difference compared to unstimulated cells was observed in TNF-α gene expression at 1.5 hours post-infection (P < 0.05)." (PMID 24721461, 2014). "In mouse models, resistance to infection or healing is associated with a TH1 response that is dependent upon expression of IL-12, IFN-γ, and TNF-α with production of nitric oxide (NO)." (PMID 25295285, 2014). "CCR5-/- mice were extremely susceptible to infection, presenting higher parasite load and lower tissue expression of IL-12p40, IFN-γ, TNF, IL-6, iNOS, Foxp3, T-bet, GATA-3 and PPARα." (PMID 25119429, 2014). "In human monocytes, the focus of this study, we have previously shown that infection with F. tularensis, leads to diminished responses of cytokines such as TNF-α, IL-6, IL-8, and IL-12 among others." (PMID 24783062, 2014). "Serum levels of TNF-α and IL-6 from the WT-infected mice decreased at 9 h post-infection, remained at high levels, and returned to basal levels at 12 h post-infection." (PMID 25264876, 2014). "Overall, splenocytes of WT and p47phox−/− mice (± T. cruzi lysate) were activated early upon infection, as is evidenced by a significant increase in TNF-α, IFN-γ and IL-10 levels at day 7 pi." (PMID 25474113, 2014). "Fibrate-treatment resulted in down-regulation of MyD88 and TNF-α expression at 1 and 6 h after infection in U937 cells." (PMID 25299393, 2014). "The immunohistological results showed that the positive cells of NLRP3, IL-1β and TNF-α altered the positive levels of original cells in tissues and infiltrated inflammatory cells which caused by H9N2 infection." (PMID 25547136, 2014). "Although TNF enhances infection of LCs, our data suggest that the level of infection does not affect transmission, since X4 viruses efficiently infected LCs butt were not transmitted to T cells." (PMID 24990163, 2014). "The adaptations for some of the cytokine trafficking pathways are strategic, such as the routing of recycling endosome membrane containing TNF to the phagocytic cup during times of infection." (PMID 25386181, 2014).
infection (continued). "(TNF-α, 1 h infection; 1.01 ± 0.07, p > 0.05, 6 h infection; 1.27 ± 0.13, p < 0.05, 12 h infection; 1.05 ± 0.05, p > 0.05, 24 h infection; 1.07 ± 0.09 p > 0.05) MyD88 expression increased significantly at 1, 6, and 12 h after M. smegmatis infection." (PMID 25299393, 2014). "This is consistent with the fact that the up-regulation of different cytokine encoding genes such as IL-1β, TNFα and CCL4 by MEC is restricted at the very early stages of infection, before a decrease at 30 hpi." (PMID 24521038, 2014). "Infection with C. rodentium produced significant increases in the hepatic mRNA expression of TNFα, IL6, IL1β, serum amyloid A (SAA), and serum amyloid P (SAP), indicative of a hepatic inflammatory response." (PMID 24707356, 2014). "MyD88 is a messenger of TLR signaling during a TB infection and TNF-α is important in the macrophage infection mechanism via TB phagocytosis." (PMID 25299393, 2014). "In contrast, circulating IL-17 and TNF-α were similar in both animal groups on day 3 post infection." (PMID 25365504, 2014). "Lower numbers of EMP and concentrations of TNF were detected in mice protected against CM during PbA infection." (PMID 24651155, 2014). "Instead, this microRNA was required for the ability of LVS-infected cells to inhibit endotoxin-stimulated TNFα secretion 18–24 hours after infection." (PMID 25295729, 2014). "Only background levels of IL-6 and TNF-α were seen with infections by the LRV-negative Lae 372 parasites, as it was observed with the Lg M4147 LRV1-negative control clone and non-infected macrophages." (PMID 24762979, 2014). "Similar to the mRNA expression, protein levels of IL-1β, TNF, IL-6, IFNγ, and IL-1α were also significantly elevated in the brains of db/db mice when compared to WT mice at day 8 after infection as measured by the multiplex immunoassay (P <0.05)." (PMID 24750819, 2014). "We therefore analysed the effect of infection with rBRSVΔSH on the level of TNF-α in the supernatant from bovine monocytes." (PMID 24700100, 2014). "The CD8+ T lymphocytes protect the host against T. cruzi through their cytolytic activity and their production of interferon-γ (IFN-γ) and tumor necrosis factor-α (TNF-α), two pro-inflammatory cytokines known to be involved in infection control." (PMID 24752321, 2014). "Similar to this study, we observed significant up-regulation chemokines and cytokines, such as CCL3, CXCL10, IL1RN, IL6 and TNF, throughout infection." (PMID 25079789, 2014). "IL10 correlated with level of infection, and hyphae and bacterial scores in the wing, and TNFα correlated with level of infection and wing hyphae score." (PMID 25391018, 2014). "TNFα was first found to be substantially increased at day 8 and decreased to the limit of detection at 29 days post-infection." (PMID 25919005, 2014). "Our data demonstrate a consistent pattern of pro-inflammatory cytokine production by C. jejuni-specific CD4+ T cells following primary infection, which included IFNγ, TNF-α, IL-2, and the chemokine, MIP-1β." (PMID 25397604, 2014). "It is worth noting that the protection induced by many vaccines against helminths, particularly S. mansoni experimental infection, has been associated with high IFN-γ and TNF-α production." (PMID 25122166, 2014). "In the IB3-1 CF cellular model, NF-κB dependent genes, including the gene coding for the proinflammatory protein IL-8, generally are activated following infection with P. aeruginosa, or treatment with TNF-α or IL-1β." (PMID 23935691, 2013). "Infection with Chlamydia in the genital tract (GT) induces the production of several pro-inflammatory cytokines such as TNF-α, IL-1, and IL-6, chemokines such as IL-8, and inflammatory cytokines including IL-12, IFN-γ, and IL-17." (PMID 23483844, 2013). "Macrophages line the peritoneal cavity and have an autonomous 24-hour clock that regulates phagocytosis and the rhythmic secretion of TNF and IL-6 in response to infection, with peak activity late in the day." (PMID 24160251, 2013).
infection (continued). "Here we aimed to identify the cellular source of IL-12/IL-23p40 and TNF-α in the acute phase of infection." (PMID 23650544, 2013). "The expression profile of TLRs on individual cells is modulated by infections and inflammatory mediators (e.g., tumor necrosis factor-α, interleukin-1β, etc.), thereby influencing the outcome of the immune responses." (PMID 24244872, 2013). "The lack of induction of classical inflammatory mediators, including IL1-β and TNF-α, during early infection has led to the suggestion that F. tularensis evades detection by host innate immune surveillance and/or actively suppresses inflammation." (PMID 23690939, 2013). "IL-10 KO and wild-type mice were infected with B. abortus and 24 hours after infection serum IL-12, IL-17, TNF-α and IFN-γ levels were determined in these mice." (PMID 24069337, 2013). "Innate immune signaling molecules such as TLR, NOD, MyD88, and pro-inflammatory cytokines such as IFN-γ and TNF-α play key roles in regulating control of infection." (PMID 23508691, 2013). "Upon infection with E. papillata, there was a significant increase in the mRNA expression of TNF-α, iNOS, IFN-γ, and IL-1β." (PMID 24367242, 2013). "These responses, which are organized to fight against the infection, are triggered by proinflammatory cytokines such as interleukin (IL)-1β, tumor necrosis factor-alpha (TNF-α), and IL-6." (PMID 24349401, 2013). "Having received anti-TNF-alpha treatment for a long time, the patient was evaluated for possible malignancy and/or specific infection and the anti-TNF-alpha drug was discontinued." (PMID 24324911, 2013). "In vivo, TNFα contributes to monocyte maturation after recruitment, whereas IL-6 supports the transition between the early stages of the infection and the sustained mononuclear influx into the infected gastric mucosa." (PMID 23970881, 2013). "In this context, the capacity of F4/80+CD11b+, F4/80lowCD11b+ and MHCII+CD11chigh cells to produce cytokine (TNF-α and IL-12/IL-23p40) was evaluated seven days post-infection." (PMID 23650544, 2013). "CSFV infected cells induced to express high levels of IFN-α, IFN-β, IL-1β, IL-6 and TNF-α in a dose-dependent way within 24 h post-infection (hpi)." (PMID 24034559, 2013). "Subsequently, TNF orchestrates destruction of superfluous immune cell clones to reduce inflammation and tissue damage once the infection is resolved." (PMID 24391650, 2013). "In comparison, in mycobacteriophage D29 treated mice, significant levels of TNF were detectable at day 68 post-infection (day 35 post-treatment)." (PMID 23638204, 2013). "Bacteria recovered from inflamed lungs at day 6 were incapable of eliciting TNF from BMDMs as is observed in the lungs at this same point in time during natural infection." (PMID 23554897, 2013). "This is in agreement with earlier reports and can be explained by the observation that TNF-α and IL-1β are produced early after infection and are removed quickly from the circulation." (PMID 23717702, 2013). "Bacterial endotoxin (lipopolysaccharide; LPS) is a potent factor in infection, which induces M1 macrophages resulting in higher levels of iNOS, TNFα and IL-12p70 which dictate inflammatory T cell responses." (PMID 23724011, 2013). "In this regard, during infection of murine macrophages with Mycobacterium avium, C3-depletion results in a significantly higher level of TNFα production." (PMID 23359218, 2013). "Significance of TNF-alpha can be evaluated by this fact that several human pathogens have evolved mechanisms to combat TNF-alpha-mediated response against infection." (PMID 24453421, 2013). "Jurkat cells infected with HIV have a transient resistance to apoptosis induced by tumor necrosis factor (TNF) and cyclohexamide at 48 h after infection, which reverses at 72 h." (PMID 23275944, 2013). "The mRNA expression of IFN-γ, IL-1β, IL-6 and TNF in the frontal cortex and hippocampus of control and infected mice on day 5 post-infection were estimated by quantitative real time PCR." (PMID 24180288, 2013).